CLSPN (claspin)
Diseases named in the same sentence as CLSPN in open-access papers (continued):
Sharing a sentence is not in itself a finding about the gene and the disease.
myotonic dystrophy type 1 (1 paper, 2023). Steinert disease, also known as myotonic dystrophy type 1, is a muscle disease characterized by myotonia and by multiorgan damage that combines various degrees of muscle weakness, arrhythmia and/or cardiac conduction disorders, cataract, endocrine damage, sleep disorders and baldness. "In human cells, depletion of TIM, TIPIN, or CLASPIN greatly accelerates CTG(n)·CAG(n) repeat expansion, thus resulting in the chromosomal instability associated with myotonic dystrophy type 1 (DM1)." (PMID 36892674, 2023).
non-alcoholic steatohepatitis (1 paper, 2022). "Little is known about the role of Claspin, or other checkpoint proteins, in non-alcoholic steatohepatitis (NASH)." (PMID 36240068, 2022).
oral squamous cell carcinoma (1 paper, 2024). "This study will explore the presence of four CLSPN SNPs including rs12058760, rs16822339, rs535638 and rs7520495 gene polymorphisms, and analyze the expression of these genes in 304 cancer-free controls and 402 oral squamous cell carcinoma (OSCC) cases." (PMID 38256171, 2024).
osteosarcoma (1 paper, 2022). A usually aggressive malignant bone-forming mesenchymal neoplasm, predominantly affecting adolescents and young adults. "In our parallel study, we have also observed reduced Claspin mRNA levels in isolates of the osteosarcoma cell line, U2OS that we have adapted over time to develop resistance to the CCT244747." (PMID 36240065, 2022).
prostate adenocarcinoma (1 paper, 2021). "We observed that CLSPN expression increased in NEPC compared with that in conventional prostate adenocarcinoma (ADPC)." (PMID 34240817, 2021).
testicular cancer (1 paper, 2024). A primary or metastatic malignant neoplasm that affects the testis. "The reduced amount of claspin, presented at the S phase, also demonstrated that testicular cancer cells exposed to IATL tended to accumulate at the sub-G1 phase." (PMID 39382942, 2024).
viral infections (1 paper, 2024). "During viral infections, the expression of CLSPN could be upregulated in response to DNA damage induced by viral replication processes." (PMID 39066192, 2024).
cancer (46 papers, 2012 to 2025). A tumor composed of atypical neoplastic, often pleomorphic cells that invade other tissues. "Increased Claspin expression has been detected in a variety of cancer samples and cell lines and was associated with reduced patient survival." (PMID 41009395, 2025). "Of note, one of the main distinctive features of cancer stem cells is their high proliferation rate, which is associated with high RS and, consequently (and physiologically), with increased Claspin expression and activity." (PMID 41009395, 2025). "Several studies associate Claspin expression in the tumor with increased cancer cell proliferation and tumor progression, namely migration, invasion, and metastasis formation." (PMID 41009395, 2025). "Cancer occurrence and progression are significantly affected by Claspin (CLSPN) gene polymorphism present in the population, which alters the expression, function, and regulation of the gene." (PMID 38256171, 2024). "CLSPN is thought to act as a tumor suppressor via ATR-CHEK1 pathway activation and DNA repair, but reports have also shown that CLSPN can support tumor survival and is associated with poor prognosis in various types of cancers." (PMID 36902377, 2023). "DNA mismatch repair genes were highly associated with the CLSPN expression in almost all cancer types." (PMID 37268895, 2023). "CLSPN expression was generally upregulated in most cancer types and was significantly associated with prognosis in different tumor samples." (PMID 37268895, 2023). "Accumulated evidence testified that CLSPN variants were correlated with susceptibility to cancers as well as sporadic tumorigenesis." (PMID 37268895, 2023). "Our findings demonstrate that TRIM21 suppresses CHK1 activation by preferentially targeting CLASPIN for K63-linked ubiquitination, providing a potential target for cancer therapy." (PMID 35048968, 2022). "In order to try to isolate more CLSPN variants associated with cancer, we also decided to characterize a set of cell lines commonly used as in vitro cancer models." (PMID 32847043, 2020). "We next analysed the genotypic and allelic frequencies of the CLSPN variants, as well as their possible association with cancer." (PMID 32847043, 2020). "Nevertheless, Claspin enhanced expression has been detected in a variety of cancer samples and cell lines and was associated with a worse prognosis." (PMID 32847043, 2020). "Altogether, the herein described data along with current literature highlight the importance of Claspin in cancer and the need for further studying Claspin genetic variants and their biological impact." (PMID 32847043, 2020). "CLSPN silencing was associated with decreased Erk and Akt phosphorylation, which may lead to reduced cancer cell survival." (PMID 41009395, 2025). "CLSPN truncating mutations have been detected in cancer samples in other studies." (PMID 41009395, 2025). "Claspin expression was also associated with resistance to chemotherapy in several cancers." (PMID 41009395, 2025). "CLSPN genetic variants are rather common in cancer and may have implications on Claspin’s function and availability." (PMID 41009395, 2025). "Our study found out that CLSPN was significantly overexpressed in different tumor tissues, and the upregulated expression of CLSPN was closely associated with stage and clinical outcomes of human cancers." (PMID 37268895, 2023). "Moreover, CLSPN was associated with immune cell infiltration in cancers, providing a potential therapy target for future cancer treatment." (PMID 37268895, 2023). "CLSPN is known to be a multifunctional protein, acting as a tumor suppressor in some cases and as a tumor progressor associated with poor prognosis in different types of cancers." (PMID 36902377, 2023). "It has been found that the cancer cells could benefit from overexpressing Claspin and Timeless to counteract the replication stress caused by oncogene-induced rapid firing of DNA replication." (PMID 37827695, 2023).
cancer (continued). "One mutant (I783S) found in both cell lines and tumour samples was found to result in loss of function, hence it is hypothesised that CLSPN mutation or loss may result in a predisposition to cancer." (PMID 36240068, 2022). "In this study, we demonstrate that in response to replication stress, over-expression of TRIM21 in cancer cells ubiquitinates CLASPIN with K63-linkage type, which counteracts its K6-linked ubiquitination, thus compromising CHK1 activation and stability of stalled replication forks." (PMID 35048968, 2022). "CLSPN c.1574A>G was significantly associated with cancer in our study." (PMID 32847043, 2020). "In our study, the CLSPN c.2230T>C variant was only detected in cancer patients." (PMID 32847043, 2020). "Therefore, in this study, CLSPN variants were investigated regarding their functional impact and potential contribution towards cancer susceptibility." (PMID 32847043, 2020). "In addition, Claspin gene (CLSPN) mutations that affect checkpoint regulation have been identified in cancer patients, suggesting that they may contribute to cancer development." (PMID 41009395, 2025). "Thus, another explanation for the observed discrepancies in the literature concerning Claspin’s role in cancer may originate from different patterns of association with other proteins that are mutated or whose expression is also altered in tumors." (PMID 41009395, 2025). "Furthermore, elevated expression of CLSPN is closely related to the induction of immune cell infiltration, tumor mutation burden, microsatellite instability, mismatch repair, and DNA methylation in various cancer types." (PMID 38256171, 2024). "Note that this analysis only takes into account expression levels in developed tumours, the association of high CLSPN levels with poor prognosis may reflect a situation where this pathway is used to cope with high levels of DNA replication stress in some cancers." (PMID 36240068, 2022). "In addition, Claspin gene (CLSPN) mutations that affect checkpoint regulation were identified in cancer patients suggesting that they may contribute to cancer development." (PMID 32847043, 2020). "In addition, we identified three heterozygous candidate missense variants in known cancer susceptibility genes (BMPR1A,BRIP1, and SRC), three truncating variants in possibly novel cancer genes (CLSPN,SEC24B, SSH2) and four candidate missense variants in ACACA, NR2C2, INPP4A, and DIDO1." (PMID 30809968, 2019). "Claspin should be considered a tumor suppressor, as its inactivation should facilitate cancer cell development through genome instability and the accumulation of genetic changes." (PMID 41009395, 2025). "Mounting evidence places Claspin as a central component in acquired radio- and chemoresistance and cancer survival." (PMID 41009395, 2025). "In this review, we will focus on the role of Claspin in cancer and ways in which Claspin can be exploited in cancer therapy." (PMID 41009395, 2025). "In summary, Claspin over-expression in tumors and, particularly, in therapy-resistant tumors, appears to be an adaptation mechanism of cancer cells to cope with the stress imposed by therapy." (PMID 41009395, 2025). "For instance, over-expression of Claspin and Tim promoted the survival of cancer cells by enabling adaptation to oncogene-induced replication stress." (PMID 41009395, 2025). "This sustained Claspin expression can also be important for the survival of cancer cells, as Claspin degradation is required for apoptosis induction when the DNA damage is too extensive, as is usually the case in cancer cells." (PMID 41009395, 2025). "In this review, we will try to integrate the currently available data on the role of Claspin in cancer and discuss how Claspin can be exploited in patients’ follow-up and cancer treatment." (PMID 41009395, 2025).
cancer (continued). "NF-kB can act as a tumor suppressor and prevent cancer development through the activation of the Claspin–Chk1-mediated checkpoint response, which, early in carcinogenesis, will prevent the accumulation of genetic mutations." (PMID 41009395, 2025). "A somatic truncating mutation in CLSPN, p.Arg1040Ter (NP_071394.5), corresponding to the cDNA change c.3118C>T (NM_022111.5), was identified in a study that aimed at identifying novel candidate cancer genes that could account for early onset (<40 years) colorectal cancer." (PMID 41009395, 2025). "As a result of further study of the Chk1 binding domain of phosphorylated CLSPN, it has been established that Cdc7 is necessary for the interaction between CLSPN and Chk1 in human cancer cells." (PMID 38256171, 2024). "Melatonin regulated the protein expressions of the HIF-1α and Bcl2 pathways’ downstream proteins, including MCL1, Bcl-XL, Bax, claspin, and survivin, which possess anti-cancer effects in numerous cancer cell types." (PMID 37086261, 2023). "Here, we first performed an integrative pan-cancer analysis to evaluate the diagnosis and prognostic value of CLSPN in various cancers." (PMID 37268895, 2023). "Previous studies had reported that CLSPN overexpression promoted docetaxel and radiation resistance in cancer patients." (PMID 37268895, 2023). "Our multi-omics analysis offers a systematic understanding of the roles of CLSPN in pan-cancer and provides a potential target for future cancer treatment." (PMID 37268895, 2023). "Firstly, we compared CLSPN expression levels among tumors and matched normal tissues from 33 cancers using the TIMER database." (PMID 37268895, 2023). "Growing researches suggest that CLSPN expression increases in several human cancers and is closely correlated with patients' survival rate." (PMID 37268895, 2023). "Accordingly, we further investigated the correlation between TME and CLSPN expressions using the ESTIMATE algorithm across 33 cancer types." (PMID 37268895, 2023). "Algorithms of CIBERSORT and XCELL were applied to analyze the correlation of infiltrating immune cells and CLSPN expression in various cancers." (PMID 37268895, 2023). "The results of Cox proportional hazards model demonstrated that CLSPN was significantly connected with OS in most cancers (P < 0.05)." (PMID 37268895, 2023). "Next, we analyzed the data from CellMinerTM to investigate the IC50 values of anti-cancer drugs and CLSPN expression." (PMID 37268895, 2023). "This experimental model of Claspin haploidy establishes Claspin as a pleiotropic regulator of normal physiology and cancer initiation and development." (PMID 36416754, 2022). "Among the frequently selected genes, it was reported that cancer cells are kept from oncogene-induced replication stress by overexpression of CLSPN." (PMID 36077657, 2022). "Claspin expression is highly variable in cancer, with low levels frequently correlating with poor patient survival." (PMID 36240068, 2022). "This work establishes Claspin as a tumor suppressor, particularly in the model of cancer initiation during recovery from damage to liver tissue." (PMID 36416754, 2022). "It has been reported that the Tim and Claspin are overexpressed in cancers and help in adaptability under replication stress." (PMID 34608864, 2021). "Claspin is a multifunctional protein that participates in physiological processes essential for cell homeostasis that are often defective in cancer, namely due to genetic changes." (PMID 32847043, 2020). "For instance, a recent study demonstrated that overexpression of Claspin and Timeless promoted survival of cancer cells by enabling adaptation to oncogene-induced replication stress." (PMID 32847043, 2020). "Given the crucial functions of Claspin in genomic protection and cell homeostasis, one can predict a role for Claspin in cancer." (PMID 32847043, 2020).
cancer (continued). "We confirmed that Claspin and Timeless protein levels are much higher in cancer cell lines relative to immortalized fibroblasts, which is consistent with earlier studies." (PMID 30796221, 2019). "Altogether, these data indicate that the overexpression of Claspin and Timeless in cancer cell lines promotes cell growth independently of their checkpoint function." (PMID 30796221, 2019). "It is, therefore, likely that the adaptation to oncogene-induced RS mediated by enhanced Claspin and Timeless occurs at the expense of genome integrity and would therefore promote cancer progression." (PMID 30796221, 2019). "The following results presented in this study show that Cdc7 is predominantly responsible for phosphorylation of CKBD of Claspin in response to replication stress in most of the cancer cells." (PMID 31889509, 2019). "Even so, the cancer cells still had some Chk1 activation, which meant that they must be able to activate some of their Claspin." (PMID 31889509, 2019). "Altogether, these data indicate that cancer cells adapt to RS by overexpressing Claspin and Timeless, independently of ATR signaling." (PMID 30796221, 2019). "Altogether, these data indicate that enhanced levels of Claspin and Timeless represent a gain of function that protects cancer cells from of oncogene-induced RS in a checkpoint-independent manner." (PMID 30796221, 2019). "We, therefore, propose that enhanced levels of Claspin and Timeless protect cancer cells from endogenous RS in a checkpoint-independent manner." (PMID 30796221, 2019). "In any case, we report here that the reduction of Claspin and Timeless levels in cancer cell lines reduced the speed of fork progression, increased the rate of fork stalling and increased γ-H2AX levels in checkpoint-proficient cells." (PMID 30796221, 2019). "Claspin and Hsp70 activation is unique in compound 19 treatments and it is distinct from other cancer cell line HCT116." (PMID 31360301, 2019). "Here, we show that Cdc7 is required for Claspin-Chk1 interaction in human cancer cells by phosphorylating CKBD (Chk1-binding-domain) of Claspin." (PMID 31889509, 2019). "Many studies have shown dysregulation of the components of the ATR-Claspin-Chk1 pathway in different cancers." (PMID 31362447, 2019). "In summary, our findings in this report show that Cdc7 is a major kinase that mediates phosphorylation of CKBD of Claspin in response to replication stress, especially in Cdc7-overexpressing cancer cells." (PMID 31889509, 2019). "This is reminiscent of the correlation observed at the mRNA level in cancer patients and supports the view that Claspin, Timeless, and CHK1 are part of a functional module whose function is distinct from the ATR signaling pathway." (PMID 30796221, 2019). "As in cancer cell lines, the depletion of Claspin and Timeless in these clones increased oncogene-induced RS, stressing the importance of these proteins the adaptation to stress." (PMID 30796221, 2019). "Another important question raised by our study concerns the mechanism by which cancer cells overexpress Claspin and Timeless." (PMID 30796221, 2019). "Functional analyses in vitro and in vivo indicated that the expression TopBP1 and Claspin positively affects the survival of cancer cells and thus negatively the xenograft metastasis model animals." (PMID 25216549, 2014). "The expression levels of TopBP1 and Claspin were increased in the cancer cells that survived radiation therapy." (PMID 25216549, 2014). "We found that the expression levels of TopBP1 and Claspin were significantly increased in the surviving cancer cells after radiation therapy compared to untreated cells." (PMID 25216549, 2014).